RCCD1 (RCC1 domain containing 1)
Description:
Plays a role in transcriptional repression of satellite repeats, possibly by regulating H3K36 methylation levels in centromeric regions together with KDM8. Possibly together with KDM8, is involved in proper mitotic spindle organization and chromosome segregation. Plays a role in regulating alpha-tubulin deacetylation and cytoskeletal microtubule stability, thereby promoting cell migration and TGF-beta-induced epithelial to mesenchymal transition (EMT), potentially through the inhibition of KDM8.
Synonyms: MGC14386
Tractability: Small molecule: a structure with a bound ligand is known. Antibody: its Gene Ontology location is reachable by antibodies, with high confidence; the Human Protein Atlas places it where antibodies can reach. PROTAC: ubiquitination databases record sites on it.
Gene: Protein-coding gene on chromosome 15 (90,954,825 to 90,964,809, forward strand). Ensembl gene ENSG00000166965.
Subcellular location: Chromosome
Subcellular location (Human Protein Atlas): Cytosol; Plasma membrane
Pathways (Reactome):
Metabolism of proteins: Protein hydroxylation
Gene Ontology:
Molecular function: protein binding
Cellular component: chromosome; cytosol; plasma membrane
Genetic constraint (gnomAD): Loss-of-function variants: 48 observed, 36.02 expected, observed/expected ratio (o/e) 1.33, 90% interval 1.06 to 1.69. The synonymous counts are far from expectation, so gnomAD's model fits this gene poorly and the ratio says little. Missense variants: 577 observed, 437.33 expected, observed/expected ratio (o/e) 1.32, 90% interval 1.23 to 1.41. Synonymous variants: 263 observed, 188.81 expected, observed/expected ratio (o/e) 1.39, 90% interval 1.26 to 1.54.
Homologues: Orthologues: chimpanzee RCCD1 (99% identical), macaque RCCD1 (93% identical), pig RCCD1 (82% identical), dog RCCD1 (77% identical), guinea pig RCCD1 (75% identical), rat Rccd1 (74% identical), mouse Rccd1 (74% identical), rabbit RCCD1 (56% identical), tropical clawed frog rccd1 (43% identical), zebrafish rccd1 (40% identical), Drosophila melanogaster CG6678 (29% identical), Drosophila melanogaster ca (23% identical), and 5 more. Paralogues in human: HERC1 (30% identical), ALS2 (27% identical), RCC1L (21% identical), RCC1 (18% identical), RCC2 (15% identical), RPGR (15% identical), RCBTB2 (15% identical), SERGEF (14% identical), RCBTB1 (13% identical).
Diseases named in the same sentence as RCCD1 in open-access papers:
RCCD1 is named in the same sentence as 10 diseases in open-access papers, as found by Europe PMC text mining. Sharing a sentence is not in itself a finding about the gene and the disease. The quoted sentences say what the papers report.
breast carcinoma (5 papers, 2017 to 2025). "The effect alleles of both rs2290203 and rs8037137 decrease RCCD1 expression, aligning with our finding that lower RCCD1 expression is associated with increased breast cancer risk." (PMID 28362817, 2017). "We found that lower predicted expression of RCCD1 (i.e., RCC1 domain containing 1) in both breast tissue and whole blood was associated with increased breast cancer risk." (PMID 28362817, 2017). "Notably, decreased expression levels of RCCD1 in whole blood (as in breast tissue) were suggestively associated with breast cancer risk (p-value: 1.2x10-05)." (PMID 28362817, 2017). "Among the 20 RCCD1 eQTL SNPs, rs3826033 (p-value: 4.1x10-03) and rs2290202 (p-value: 5.3x10-03) contributed the most weight to prediction (33% and 29% respectively) and were the most strongly associated with breast cancer risk." (PMID 28362817, 2017). "It is thus plausible that lower expression of RCCD1 could lead to errors in cell division that could potentially increase the risk of breast cancer." (PMID 28362817, 2017). "In trans-ethnic meta-analyses of U4C and UK Biobank data, we found significant associations between breast cancer risk and the expression of RCCD1 (joint p-value: 3.6x10-06) and DHODH (p-value: 7.1x10-06) in breast tissue, as well as a suggestive association for ANKLE1 (p-value: 9.3x10-05)." (PMID 28362817, 2017). "Future studies should evaluate the specific mechanisms whereby reduced RCCD1 expression could be associated with breast cancer risk." (PMID 28362817, 2017). "Of note, RCCD1 and LRRC25 were identified as likely targets of known breast cancer risk variants in our analysis." (PMID 30988301, 2019). "All four genes were near (<500 kb) breast cancer SNPs previously identified by GWAS11, and two genes (L3MBTL3 and RCCD1) also were reported by prior breast cancer TWAS 14,15,32." (PMID 36690614, 2023). "While RCCD1 and ANKLE1 have been implicated by GWAS of breast cancer risk, DHODH has not been previously identified." (PMID 28362817, 2017). "While genome-wide association studies (GWAS) have implicated RCCD1 and ANKLE1 in breast cancer risk, they have not identified the remaining three genes." (PMID 28362817, 2017).
lung carcinoma (1 paper, 2025). "The lead variant rs12441109-G exhibits a regulatory role on the expression of the neighboring gene RCCD1, which is involved in chromatin organization and is recognized as a novel oncogene in lung cancer." (PMID 40869924, 2025).
ovarian carcinoma (1 paper, 2021). A malignant neoplasm originating from the surface ovarian epithelium. "In the OV_BRCA1 group, we observed overexpression of RCCD1, which was previously identified as a susceptibility locus for ovarian cancer, and of SUSD2, which promotes cancer metastasis and associates with cisplatin resistance." (PMID 33525353, 2021).
schizophrenia (1 paper, 2026). A major psychotic disorder characterized by abnormalities in the perception or expression of reality. "Targets were next examined in the adult rodent (postnatal day70) brain, and a subgroup of these genes (i.e., Furin, Rps10, and Rccd1) were increased concomitant with schizophrenia-like behavior (e.g., decreased pre-pulse inhibition)." (PMID 40827685, 2026). "Placentae from ∆9-tetrahydrocannabinol-exposed males and females revealed altered expression of genes previously identified in human transcriptomic datasets of schizophrenia (i.e., Furin, Rccd1, and Atp5mk), with some expression changes being sex-specific (i.e., Eif5, Rps10, Vps33b, and Iqgap1)." (PMID 40827685, 2026).
tumor (3 papers, 2025 to 2026). "RGS13 is predominantly expressed in macrophages, while RCCD1 is expressed at low levels in various cell types within the tumor microenvironment." (PMID 40161374, 2025). "RCCD1 promotes the migration of tumor cells and TGF-β-induced EMT." (PMID 40869924, 2025).
neurodevelopmental disorder (1 paper, 2023). A behavioral and cognitive disorder with onset during the developmental period that involves impaired or aberrant development of intellectual, motor, or social functions. "Whether a similar neurodevelopmental disorder might arise as a consequence of inheriting pathogenic variants in genes encoding functional partners of JMJD5, such as RCCD1, is also of interest." (PMID 36795492, 2023).
RCCD1 also shares sentences with these, for which no sentence is quoted: cancer (2 papers); Colon Cancer (1); colorectal cancer (1); migraine (1).